CD44 (CD44 molecule (IN blood group))
Diseases named in the same sentence as CD44 in open-access papers (continued):
Sharing a sentence is not in itself a finding about the gene and the disease.
cancer (continued). "The alternative splicing triggers the variant isoform of CD44, and the expression level is a critical regulator in various cancers." (PMID 34513617, 2021). "So far, different CD44 splice variants have been described to affect tumorigenesis, cancer stemness and drug resistance, e.g., CD44v3 promotes progression of urothelial carcinomas through AKT/ERK/STAT3 pathways." (PMID 33924987, 2021). "GO enrichment revealed major biological processes and pathways associated with CCND1/CDK4/PLK1/CD44 in different cancers." (PMID 34063946, 2021). "Another important player that is associated with cancer development/metastasis is a cluster of differentiation 44 (CD44) in its standard (CD44s) and variant (CD44v) form." (PMID 33540535, 2021). "EMT causes an increase in cancer stem cell phenotypes, which are characterized by markers such as Oct-4, Nanog, CD44, and CD133." (PMID 34885003, 2021). "This review discusses the involvement of CD44 in association with TEVs in cancer progression with the emphasis on ‘pre-metastatic’ niche formation and metastasis." (PMID 33540535, 2021). "Although the functions of CD44 and its variants in cancer development have been well studied, the obvious molecular mechanism of CD44 related to redox status regulation contributing to CCA progression and metastasis is yet to be elucidated." (PMID 33780455, 2021). "It is associated with an increased expression of cancer stem cells (CSCs) markers—CD44 and CD133 and with a loss of estrogen receptors (ER), progesterone receptors (PR), and decreased E-cadherin." (PMID 34574048, 2021). "CD44 is a ubiquitous cell surface adhesion molecule implicated in cancer development and metastasis, promoting invasion and angiogenesis." (PMID 33672684, 2021). "The results show that the four ferroptosis suppressor genes were all positively associated with CD133 and CD44 (P < 0.05), which were consistent with the results of cancer stemness feature analysis." (PMID 34434214, 2021). "In the same cancer, CD44 overexpression was positively associated with progressive histologic grade and FIGO stage." (PMID 34944493, 2021). "We found that CD44, which encodes a glycoprotein over expressed in cancer stem cells, was up regulated in WM B-cells." (PMID 33921415, 2021). "In HCC, a cell population expressing the mesenchymal and stem cell-associated marker CD44 together with the stem cell marker CD133 has been described as cancer progenitor cells with invasive capacity." (PMID 33953226, 2021). "The hyaluronan-CD44 axis plays two essential roles in cancer: it creates a dense ECM in association with collagen and integrins and forms part of signaling pathways that participate in cellular motion, invasion, and metastasis." (PMID 33921242, 2021). "SeNP in MCF–7 cancer cells cause an increase in the expression of cytochrome C, Bax, and P—p38, a decrease in CD44, which leads to disorganization and dysregulation of intracellular cytoskeleton F-actin, and induction of apoptosis and necrosis." (PMID 34439975, 2021). "CD44 is a well-known marker of cancer stem cells and is implicated in intercellular adhesion, cell migration, cell spatial orientation, and promotion of matrix-derived survival signal." (PMID 34332294, 2021). "CD44 is often aberrantly expressed in cancer and it is also associated with epithelial-to-mesenchymal transition, a crucial event in cancer progression." (PMID 33671476, 2021). "The expression of HeyL, together with the stemness-associated genes SOX2, OCT4, KLF4, and CD44, was significantly increased in PCSCs compared with the corresponding bulk cancer cells." (PMID 35096586, 2021). "We observed many significantly enriched interactions between the CDH12 population and fibroblasts, with the most notable being TGFBR1, CD44, and several integrins because of their involvement in cancer-associated fibroblast (CAF) activation." (PMID 34385456, 2021).
cancer (continued). "CD44 increases the metastatic potential of carcinoma cells, while reduced expression of ECAD is associated with differentiation and metastasis." (PMID 35008821, 2021). "The cancer stem-like cells with CD44 variant 9, one of the isoforms that has been shown to enhance metastasis, contribute to the development and recurrence of gastric cancer and failure of cancer chemotherapies." (PMID 33050101, 2020). "CD44 expression is usually associated with cancer stem cell characteristics and is considered a marker of these cells in most tumors." (PMID 32610620, 2020). "Several SNPs of CD44 have been reported to have significant correlations with the risk of various cancers in Asians." (PMID 32344833, 2020). "Cytoskeleton protein complex involving with association of CD44 and ERMs is critical for cancer-related cellular adhesion and migration." (PMID 32271757, 2020). "Subsequent researches showed that CD44 cross-linking has been associated with the progression of other human cancers." (PMID 33292278, 2020). "CD44 is also shown to be associated with treatment resistance and CD44 expression is correlated with poor survival of many types of human cancers." (PMID 32434417, 2020). "FNI/II/IV binds CD44, a transmembrane glycoprotein implicated in cancer development and progression." (PMID 32260326, 2020). "Further studies in a larger scalewith taking the advantage of validation of the proposedmiR-570-mediated mechanistic effect of rs8193 on theexpression of CD44 can more clarify the significance ofdifferent rs8193 alleles in cancer." (PMID 31376327, 2020). "SOX2 takes part in cancer stemness and its expression has been associated with CD44 and ALDH1 expression and correlated with oral squamous cell carcinoma (OSCC) metastasis." (PMID 32635524, 2020). "One of the common markers is CD44 and its splice variants and this is why it has been of such interest in cancer research." (PMID 32429122, 2020). "High expression of CD44, including some of its alternatively spliced variants, is seen in cancer stem cells and is thought to play a role in cancer development and progression." (PMID 33008022, 2020). "In 2011, the transmembrane glycoprotein CD44, a cancer stem-like cell marker, and more precisely the CD44 variant (CD44v) capable to bind hyaluronan has also been described to interacts and stabilizes Xc- system." (PMID 32457843, 2020). "Several studies have shown that CD44 proteolytic cleavage is linked to cancer progression and metastasis, demonstrating that the release of CD44 is associated with presenilin-dependent γ-secretase and membrane-associated metalloprotease activity." (PMID 33062960, 2020). "Haloperidol was associated with a significant decrease in CD24 and CD44, both of which have been related to cancer stem cells." (PMID 33322363, 2020). "CD44 standard splice isoform promote cancer stem cell traits, but the CD44 variant splice isoforms exhibit an inverse role." (PMID 32939931, 2020). "Altered CD44 expression was associated with the aggressive clinicopathological characteristics of various human cancers." (PMID 32711494, 2020). "CD44, also known as a stem cell-associated maker in various types of cancer, is required for the cellular uptake of polyR-conjugated molecules." (PMID 32977522, 2020). "CD44 expression is increasingly associated with the stemness characteristics of cancer cells, although the presence of cancer stem cells in NSCLC subtypes remains equivocal." (PMID 33014869, 2020). "CD44 is a well-known cancer stem cell-associated marker which has also been reported to participate in CLL cell survival." (PMID 32517377, 2020). "CD44 is overexpressed in CSCs, frequently shows alternative spliced variants, and plays a role in cancer development and progression." (PMID 34841087, 2020). "CD44 is known as a surface marker associated with CSC in various cancer types, and several CD44 variant isoforms are generated by alternative splicing processes." (PMID 32039729, 2020).
cancer (continued). "CD44 was implicated in poor prognosis, cancer cell invasion, metastasis, and resistance to the sunitinib treatment." (PMID 33046980, 2020). "CD44+/CD24- expression is associated with cancer stem like properties, chemoresistance and more invasive capacity." (PMID 32544183, 2020). "One of the CD44 variants, CD44v6, was first identified as contributing to cancer metastasis, and CD44v6-specific monoclonal antibodies (mAbs) were found to inhibit metastasis of rat pancreatic cancers." (PMID 33000243, 2020). "High expression of CD44 in cancer cells is also associated with cancer stem cell (CSC) properties and is used as a CSC marker." (PMID 32984031, 2020). "For these reasons tremendous research efforts have been focused on studying the diagnostic and prognostic value of CD44 in cancer and how to exploit CD44 as target agent in cancer therapy." (PMID 32183027, 2020). "For example, CD44v3, CD44v6, and CD44v10 have been implicated in cancer and are the only CD44 isoforms that contain binding sites for cancer-related cytokines and chemokines." (PMID 32984308, 2020). "In many tumors (e.g., breast and liver), CD44 is expressed as isoform and its expression has been associated with increased cancer stem cell properties." (PMID 32849491, 2020). "CD44 and its splice variants are enriched in a variety of cancer cells and all of these receptors bind HA." (PMID 32429122, 2020). "It has been demonstrated that the high expression of CD44 on cancer cells is associated with increased metastasis." (PMID 33050539, 2020). "Serglycin secreted by both cancer-associated stroma cells, as well as the cancer cells themselves, binds to the transmembrane glycoprotein CD44." (PMID 33330449, 2020). "Cd44, a gene encoding multiple transmembrane protein isoforms involved in lymphocyte function and cancer metastasis, was one of the most notable examples of a large difference in exon usage between tissue layers." (PMID 33013468, 2020). "In line with the results of TCGA dataset analysis (Fig EV3D), p‐TFCP2L1 expression was more associated with cancer‐specific survival than SALL4 or CD44 expression in the BC patient cohort." (PMID 31709755, 2020). "Several studies revealed that some cancer-associated AS variants, such as CD44 and VEGF (vascular endothelial growth factor) receptor, played an important role in cancer-targeted therapies." (PMID 32547595, 2020). "In summary, here we present evidence of a physical interaction of podoplanin with CD44s and CD44v isoforms expressed in human SCC cells, suggesting a functional interplay between podoplanin and CD44 likely associated with cancer cell invasion." (PMID 33003440, 2020). "In a recent meta-analysis, Han and colleagues tried to generalize the prognostic significance of CD44 and its variant isoforms in advanced cancer patients." (PMID 32154167, 2020). "Blocking CD44 with a specific antibody hamper tumorigenic cells to coalesce, which indicates another mechanism underlying the promoting roles of CD44 in cancer initiation." (PMID 33303029, 2020). "Many studies have indicated that CD44 polymorphisms are a risk factor for susceptibility to different cancers." (PMID 32344833, 2020). "Among splicing variant isoforms, CD44 variant 8–10 (CD44v8-10) is reported to play a role in chemoresistance and to be associated with poor prognosis of several types of cancer." (PMID 32642575, 2020). "CSCs can be identified by cancer stem cell markers, and CD44 variant exon 6 (CD44v6) has been identified as one of the important markers of CSCs in many malignant tumors." (PMID 31888685, 2019). "Sam68 promotes inclusion of exon v5 in the CD44 pre-mRNA, which encodes a cell surface protein involved in cancer." (PMID 31027221, 2019). "YBX1 is also reported to regulate the expression of MAPK1, involved in cell proliferation and invasion, and CD44 and CD49f (or integrin alpha 6), the genes linked to cancer stem cells." (PMID 31358880, 2019).
cancer (continued). "Over the past decade, many studies have been conducted to examine the contribution of CD44 polymorphisms to the risk of cancer." (PMID 31301090, 2019). "The splenic immunophenotye of mice with advanced cancer showed the emergence of the hyaluronic acid receptor CD44+ and in a smaller extent IL-17A+ MDSCs, the loss of B220+ and CD62L+ B-cells, the loss of CD62L+ CD4+ and CD8+T-cells." (PMID 31881770, 2019). "Survivin and CD44 represent two important key factors for cancer development: Survivin is a crucial protein playing a role in apoptosis inhibition, whereas CD44 is a well known stemness marker associated to resistance to treatments." (PMID 30650148, 2019). "Multiple CD44 variants are markers of stem cells and cancer stem cells, and have been linked to angiogenesis and increased metastatic activity in tumors." (PMID 31394726, 2019). "Upregulation of CD44 is typical for cancer cells and cancer stem cells and is often associated with an unfavorable outcome." (PMID 30909497, 2019). "As an easily detectable surface molecule carried on the EV and their donor cells, CD44 has potential as a biomarker in cancer and other conditions associated with enhanced CD44 expression such as inflammation." (PMID 30909497, 2019). "Duodenal polyps in this study also exhibited upregulation of CD44, a cancer stem cell marker associated with PGE2 signaling, and MMP7, which encodes a matrix metalloproteinase and is a Wnt/Beta-catenin signaling target." (PMID 31211760, 2019). "In particular, a number of studies have explored the association between the CD44 rs187115 polymorphism and cancer risk, though their findings have been inconsistent." (PMID 31682231, 2019). "The expression of CD44 is associated with cancer cell invasion, metastasis, sunitinib resistance, and poor prognosis of RCC." (PMID 31950034, 2019). "In HCC, the loss of HNF4 and expression of the cancer stem cell (CSC) markers CD44, CK19, Sox9, and EpCAM are considered to be indicators for poor prognosis." (PMID 31726709, 2019). "CD44 variant 9 (CD44v9), a splicing variant of CD44, has emerged as a novel marker of cancer stemness in a variety of solid tumors." (PMID 29971631, 2019). "The T allele mutations in the CD44 rs13347 site affect gene transcriptional activity, which leads to changes in protein levels and contributes to the risk of cancer." (PMID 31301090, 2019). "For instance, CD44 reportedly interacts with podoplanin to promote cellular protrusions and provide directional cues in cancer-associated epithelial cells." (PMID 30745334, 2019). "H5B14-based ADCs also inhibited spheroid formation and caused death of cancer stem-like cells with RON+/CD44+/ESA+ phenotypes." (PMID 31519211, 2019). "CD44 is the most important HA receptor, and both have been associated with poor prognosis in cancer." (PMID 31358779, 2019). "Nine studies involving 796 advanced cancer patients evaluated the association between CD44 expression and the prognosis and only six studies evaluated 5-years survival." (PMID 30788285, 2019). "We integrated all eligible studies with a relatively large population, and found that CD44 expression was slightly linked to unfavorable OS of advanced cancer (HR = 2.03, P = 0.027)." (PMID 30788285, 2019). "CD44 is highly studied in human malignancy and specific splice-variants of CD44 have been causally related to metastatic behaviour in a variety of carcinomas." (PMID 31450747, 2019). "CD44 variant (CD44v) contributes to cancer stemness by stabilizing the xCT subunit of system xc(−) and thereby promoting its glutamate-cystine antiporter activity." (PMID 29434323, 2018). "As the characteristics of the cancer cell membrane depend on its membrane proteins, we identified five major proteins associated with cell invasion and metastasis (CD44, CD47, E-cadherin, EpCAM, and Tissue factor) using western blot." (PMID 30487569, 2018).
cancer (continued). "In contrast, CD44 variant isoforms show tissue-specific expression patterns and have been extensively studied as both prognostic markers and therapeutic targets in cancer and other diseases." (PMID 29872736, 2018). "Further, they observed the putative cancer stem cell markers CD44 and Oct4 as well as β1 integrin to be associated with poor prognosis." (PMID 30571736, 2018). "The CD44 isoform containing variant exon 9 (CD44v9) is a known marker for cancer stem-like cells in many types of cancers." (PMID 30405881, 2018). "Correspondingly, previous report showed that IL-6 treatment enhanced CD44 (variant 6) expression in cancer cells via STAT3 activation." (PMID 30473835, 2018). "For example, CD44 is a marker molecule expressed in cancer cells and has been associated with cancer cell adhesion, migration, and metastasis." (PMID 29597298, 2018). "Their results provided the bright hope of using HA on the development of CD44-targeted nanomaterials on diagnostic and therapeutic strategies for cancer." (PMID 29891947, 2018). "CD44 isoforms switching was reported to contribute to cancer metastasis associated with variant isoforms." (PMID 29747682, 2018). "In both immune cells and cancer cells, CD44 has been implicated in signaling via the PI3K/Akt pathway which promotes both proliferation and survival." (PMID 29684048, 2018). "Particular focus has been set on narrowing CD44 screening to its cancer-associated isoforms envisaging the necessary sensitivity and specificity for clinical applications." (PMID 29983670, 2018). "Cancer stem cells have a superior antioxidant defence system that includes a CD44 variant isoform containing variable exon 8–10 (CD44v8–10) and cysteine/glutamate antiporter (xCT)." (PMID 29760743, 2018). "High expression levels of CD44 are associated with drug resistance during cancer metastasis and are a marker of unfavorable prognosis in some cancers." (PMID 30544868, 2018). "CD44, a transmembrane glycoprotein, is expressed as a wide variety of isoforms in many cells, and implicated in increased cancer cell migration, invasion, and metastasis." (PMID 28460475, 2017). "Beside standard CD44 (sCD44), variant (vCD44) isoforms of CD44 have been shown to be created by alternate splicing of the mRNA in several cancer." (PMID 28326306, 2017). "The effect of CD44 polymorphisms on human cancer susceptibility and clinical outcome has been described in various human cancer studies." (PMID 29445738, 2017). "Another issue that needs further investigations is the relative roles of standard (CD44s) and variant (CD44v) isoforms of CD44 in cancer development and progression." (PMID 28460475, 2017). "CD44 has been identified as one of the cell surface markers associated with cancer stem-like cells in various solid tumors." (PMID 29445738, 2017). "Early on, expression of splice variants of CD44 such as CD44v6 was shown to stimulate metastases formation and was in the focus of cancer research." (PMID 27683128, 2017). "Since CD117 and CD44 are both associated with cancer mesenchymal stem cells (MSCs) and play a mechanistic role in regulating malignant/metastatic behavior, we tested the capability of WF pool to stimulate tumorigenesis in vitro." (PMID 29156702, 2017). "The expression of the cell surface marker, CD44, which is associated with cancer stem cells, seems to be correlated with the cells’ metastatic characteristics; cellular migration, epithelial-mesenchymal transition (EMT) expression and liver tumorigenicity." (PMID 29069721, 2017). "Recently, a number of studies have conducted the association between CD44 rs187116 polymorphisms and risk of cancer; however, the results were conflicting." (PMID 29445738, 2017). "In cancer T cells, expression of CD44 has been linked to enhanced mTOR activation as the result of RasGRP1 mutations." (PMID 29180720, 2017).